TEAD1 (TEA domain transcription factor 1)
Diseases named in the same sentence as TEAD1 in open-access papers (continued):
Sharing a sentence is not in itself a finding about the gene and the disease.
keratoconus (3 papers, 2022 to 2024). A degenerative, structural disorder of the eye, characterized by a cone-shaped protrusion of the cornea. "We also detected the up-regulation of the mechano-transducer YES-associated protein 1 (YAP1) as well as its cooperator TEA domain transcription factor (TEAD1) in keratoconus stromal cells." (PMID 35821117, 2022). "Importantly, the authors identified cathepsin D (CTSD), cathepsin K (CTSK), YES-associated protein 1 (YAP1), and TEA domain transcription factor (TEAD1) as novel biomarkers in keratoconus stromal cells." (PMID 37138096, 2023). "Remarkably, we detected significantly elevated YAP1 and TEAD1 in keratoconus stromal cells." (PMID 35821117, 2022). "To test whether the expression of YAP and TEAD changed in keratoconus, we surveyed their expression level in our data, and found that both YAP1 and TEAD1 elevated in keratoconus stromal cells, implying the response of keratoconus stromal cells to mechanical stretch." (PMID 35821117, 2022).
liver cancer (3 papers, 2022 to 2026). An epithelial or non-epithelial malignant neoplasm that arises from the liver. "Additionally, we identified that the TEA domain transcription factor 1 (TEAD1)-derived peptide effectively disrupted YAP condensate formation, leading to AMPKα activation in vivo and inhibition of primary liver cancer progression." (PMID 41486777, 2026). "Significantly, various known YAP/TEAD1 targeted genes, such as BIRC5, AREG, CCND1, CTGF, and MYC, were not activated through SRGN-mediated YAP signaling in liver cancer cell lines." (PMID 40384866, 2025).
myocarditis (3 papers, 2023 to 2025). Myocarditis is a condition that is characterized by inflammation of the heart muscle (myocardium). "Western blot data showed that XMU-MP-1 decreased the cascade of HIPPO pathway kinases as well as the expression levels of Mst1 and TEAD-1 and increased the expression of TAZ in the myocardial tissue of the ICI-related myocarditis model." (PMID 38236243, 2024). "Expressions of TEAD1 and most of its target genes were down-regulated in CMs of the patients with LMNA Q353R DCM but not of patients with other DCM or myocarditis." (PMID 37058558, 2023).
osteosarcoma (3 papers, 2022 to 2024). A usually aggressive malignant bone-forming mesenchymal neoplasm, predominantly affecting adolescents and young adults. "One study revealed that depletion of lncRNA HOXA-AS3 reduced cell proliferation, migration, invasion in osteosarcoma cells via targeting miR-1286/TEAD1 axis." (PMID 39019995, 2024). "Our previous study showed that YAP expression and activity are increased in osteosarcoma, and the development and metastasis of osteosarcoma are governed by the YAP/TEAD1 complex." (PMID 35615117, 2022).
sarcoma (3 papers, 2021 to 2025). A usually aggressive malignant neoplasm of the soft tissue or bone. "Furthermore, FOXM1 was shown to directly interact with the YAP1 transcriptional complex via TEAD1, resulting in the co-regulation of numerous critical proliferation targets that enhance sarcoma progression." (PMID 34831091, 2021).
spindle cell rhabdomyosarcoma (3 papers, 2024 to 2025). An uncommon variant of rhabdomyosarcoma characterized by the presence of whorls of spindle cells forming a storiform pattern. "Additionally, transcription factors such as FOXC1, which has been associated with the development of multiple tumors, TBX3, associated with Ulna-Mamma Syndrome, and TEAD1, linked to Neurofibroma and Spindle Cell Rhabdomyosarcoma, could be considered targets for drug repositioning." (PMID 38673810, 2024). "Several recent studies have identified the recurrent rearrangement of the VGLL2 and TEAD1 genes in a large subset of spindle cell rhabdomyosarcoma (scRMS), a pediatric form of RMS that is distinct from embryonic RMS (ERMS)." (PMID 38746415, 2025).
Sveinsson's chorioretinal atrophy (3 papers, 2012 to 2019). "On the other hand, a loss-of-function mutation in TEAD1 (Y421H) was shown to cause Sveinsson’s chorioretinal atrophy, which is a genetic disorder that results in degeneration by disrupting TEAD1-YAP interaction." (PMID 31212916, 2019). "Accumulating evidence has strongly linked TEAD1 disruption or MST kinases activation to many diseases, such as Sveinsson's chorioretinal atrophy, AC, AD, skeletal muscle atrophy, ALS and diabetes." (PMID 27805903, 2016). "This mutation causes the human genetic disease known as Sveinsson's chorioretinal atrophy, and strongly reduces both YAP/TEAD1 interaction and activity." (PMID 23029054, 2012).
Aicardi syndrome (2 papers, 2017 to 2025). Aicardi syndrome is a rare neurodevelopmental disorder defined by the triad of agenesis of the corpus callosum (total or partial), typical chorioretinal lacunae and infantile spasms that affect almost exclusively females. "It has been reported recently that de novo variants in TEAD1 and OCEL1 each may cause Aicardi syndrome in a single individual of a small cohort of females with this clinical diagnosis." (PMID 28361097, 2017). "Some studies suggest that Aicardi syndrome may not be restricted to X-linked genes, and that autosomal mutations like TEAD1 may underlie certain cases." (PMID 41573467, 2025). "A comprehensive evaluation of the described individuals with TEAD1 and OCEL1 variants by clinicians experienced with the diagnosis of Aicardi syndrome would also be helpful to distinguish any subtle phenotypic anomalies that might be specific to subjects harboring variants in these autosomal genes." (PMID 28361097, 2017). "To investigate this further, we sequenced TEAD1 and OCEL1 coding regions using DNA from 38 clinically well‐characterized girls with Aicardi syndrome." (PMID 28361097, 2017). "Although TEAD1 and OCEL1 may be rare causes of Aicardi syndrome, it is also possible that these genes may contribute to phenotypes that overlap with characteristics of Aicardi syndrome and that the phenotypic characterization of Aicardi syndrome requires refinement." (PMID 28361097, 2017).
atherosclerosis (2 papers, 2025). A disease characterized by the build-up of fatty material and calcium deposition in the arterial wall resulting in partial or complete occlusion of the arterial lumen. "Importantly, cytoplasmic expression of circ‐PIAS1‐5 alleviates miR‐219a‐2‐3p expression, causing downregulation of TEAD1 in foam cells, which consequently regulates the progression of atherosclerosis induced by Hcy." (PMID 40089857, 2025). "Taken together, these results demonstrated that circ‐PIAS1‐5 activates the AMP‐activated protein kinase pathway by regulating TEAD1 and contributes to atherosclerosis in ApoE−/− mice." (PMID 40089857, 2025). "Furthermore, we elucidated the role of TEAD1 in regulating the trans‐differentiation of VSMCs into fibroblast‐like cells via the Wnt4/β‐Catenin signaling pathway, which promoted plaque repair during the dynamic process of atherosclerosis." (PMID 39665254, 2025).
brain cancer (2 papers, 2021 to 2024). A primary or metastatic malignant neoplasm affecting the brain. "Furthermore, TEAD1 has also been shown to be part of a neuronal transcriptional network which is fundamental to the progression of the pediatric brain cancer medulloblastoma." (PMID 34088262, 2021).
cervical carcinoma (2 papers, 2012 to 2023). A carcinoma arising from either the exocervical squamous epithelium or the endocervical glandular epithelium. "We thus decided to explore the apoptotic role of the TEAD family of transcription factors, focusing on the effects of the modulation of TEAD1 expression on apoptosis in human HeLa cervical carcinoma cells." (PMID 23029054, 2012).
diabetes (2 papers, 2016 to 2025). "Altogether, the over-expression of MST1 and the deficiency of TAZ and Tead1 may interfere with the transcription of PDX1, which further leads to the dysfunction of β-cells and diabetes." (PMID 40707469, 2025). "It implies that maintaining the expression of YAP/TAZ, which can be implemented by YAP/TAZ/TEAD1 activators or inhibitors of upstream kinases (MST1/2, LATS1/2), maybe a potential target in future diabetes treatment." (PMID 40707469, 2025).
endometrial cancer (2 papers, 2017 to 2022). Primary or metastatic malignant neoplasm involving the endometrium (mucous membrane that lines the endometrial cavity). "The overexpression of TEAD1 was found to contribute to cell invasion and migration in endometrial cancer." (PMID 35739490, 2022). "In human endometrial cancer cell line Sawano, mRNAs of AREG and TEAD1 were markedly upregulated by the loss of LSR." (PMID 28071680, 2017). "The loss of LSR promoted cell invasion and migration via upregulation of TEAD1/AREG dependent on YAP/pYAP and AMOT/Merlin in human endometrial cancer cells." (PMID 28071680, 2017).
head and neck squamous cell carcinoma (2 papers, 2023 to 2025). A squamous cell carcinoma that arises from any of the following anatomic sites: lip and oral cavity, nasal cavity, paranasal sinuses, pharynx, larynx, and salivary glands. "We found that TEAD1 expression was significantly associated with higher clinical stages of multiple cancers, including adrenocortical carcinoma (ACC), BLCA, head and neck squamous cell carcinoma (HNSC), and kidney renal clear cell carcinoma (KIRC)." (PMID 40539054, 2025).
hypertrophic cardiomyopathy (2 papers, 2024). A condition in which the myocardium is hypertrophied without an obvious cause. "Next, we determined whether these changes in TEAD1 expression also occurred in hypertrophic cardiomyopathy (HCM) patients." (PMID 38374140, 2024).
renal fibrosis (2 papers, 2024 to 2025). A final common manifestation of a wide variety of chronic kidney diseases characterized by glomerulosclerosis and tubulointerstitial fibrosis. "In recent years, studies have reported that SIRT1 not only interacts with JMJD3 to inhibit macrophage polarization and SASP production, exerting mitochondrial protection and anti-renal fibrosis effects, but also interacts with TEAD1 to improve mitochondrial function and alleviate kidney injury." (PMID 40552151, 2025).
rhabdomyosarcoma (2 papers, 2023 to 2025). A rare aggressive malignant mesenchymal neoplasm arising from skeletal muscle. "Spindle cell/sclerosing rhabdomyosarcomas typically harbor certain genomic alterations, including rearrangements involving TFCP2, VGLL2, NCOA2, CITED2, TEAD1, and SRF, as well as the MYOD1 p.L122R mutation." (PMID 40361368, 2025). "Yet, Tead1 binds muscle genes that are suppressed in rhabdomyosarcoma, which is consistent with the finding that Yap and Taz can also repress gene expression." (PMID 36980284, 2023).
acute myocardial infarction (1 paper, 2022). Necrosis of the myocardium, as a result of interruption of the blood supply to the area. "KCNQ1OT1 could competitively bind with miR-466 to mediate downstream Tead1 expression, promoting apoptosis of cardiomyocytes during acute myocardial infarction." (PMID 36278219, 2022).
adenovirus infection (1 paper, 2024). "After adenovirus infection, significantly elevated TEAD1 mRNA and protein levels were confirmed in NMCFs." (PMID 38374140, 2024).
adrenocortical carcinoma (1 paper, 2025). "Expression profiling analysis of cancer cell lines showed that TEAD1 was highly expressed in adrenocortical carcinoma, non-cancerous cancers, and testicular cancer cell lines." (PMID 40539054, 2025).
Alzheimer disease (1 paper, 2020). A progressive, neurodegenerative disease characterized by loss of function and death of nerve cells in several areas of the brain leading to loss of cognitive function such as memory and language. "In learning SCR, the genes closest to two of them modulate transcription (Mir7025 and Tead1), and the gene closest to the third SCR (Slc10a2) is related to Alzheimer’s disease." (PMID 32410960, 2020).
Burkitt lymphoma (1 paper, 2021). A rare form of malignant mature B-cell non-Hodgkin lymphoma. "In support of our results here, results presented in the Human Protein Atlas database indicate that RNA transcripts of YAP, TAZ, and the four TEAD family members (TEAD1, TEAD2, TEAD3, and TEAD4) are not detected in the EBV-infected Burkitt lymphoma cell line, Daudi." (PMID 34339458, 2021).
cervical adenocarcinoma (1 paper, 2018). An adenocarcinoma arising from the cervical epithelium. "As an important component of the TEAD-1-YAP complex, YAP1 upregulation in cytoplasm is associated with histologic grading, lymph node metastasis, and recurrence of cervical SCC, and its nuclear overexpression is associated with shorter OS and disease-free survival of cervical adenocarcinoma." (PMID 30344797, 2018).
cervical tumor (1 paper, 2020). "Because TEAD1 activates the early promoter of human papillomavirus (HPV), a causative agent for cervical tumor, the contribution of VGLL1 to HPV early gene expression was recently investigated." (PMID 32793503, 2020).
chordoma (1 paper, 2024). Chordomas are rare malignant tumors arising from embryonic remnants of the notochord in axial skeleton. "Furthermore, upon actinomycin D treatment of chordoma cells, circTEAD1 exhibited a significantly longer half‐life compared to that of TEAD1." (PMID 38659080, 2024).
chronic kidney disease (1 paper, 2024). Impairment of the renal function secondary to chronic kidney damage persisting for three or more months. "Targeting Tead1 in macrophages may become effective therapeutic targets for the treatment of chronic kidney disease." (PMID 39108258, 2024). "Thus, we suggest that Tead1 as a primary downstream effector of Taz in Hippo signaling may become effective therapeutic targets for the treatment of chronic kidney disease." (PMID 39108258, 2024).
colitis (1 paper, 2025). Inflammation of the colon. "For instance, TEAD1 is a component of the Hippo pathway that has been found to exert immunomodulatory effects in murine models of colitis, and ARID5A, regulates the expression of genes downstream of the Th17/IL-17 axis, a pathway known to play a critical role in IBD pathogenesis." (PMID 40914875, 2025).
coloboma (1 paper, 2025). An abnormality in which a part of a structure in one or both eyes is missing. "Disruption of this signaling axis has been implicated in congenital ocular conditions such as SCRA and coloboma, underscoring the essential role of TEAD1 in retinal and optic nerve development." (PMID 40984966, 2025).
congenital heart disease (1 paper, 2022). A heart disease that is present at birth. "These published data highlight the importance of YAP and TEAD1 in heart development and suggest that investigating YAP and TEAD1 modulators may be a productive strategy to dissect the molecular mechanisms underlying congenital heart disease." (PMID 36139407, 2022).
diabetic cardiomyopathy (1 paper, 2020). Diabetic cardiomyopathy is a disorder of the heart muscle in people with diabetes. "Furthermore, the YAP1/TEAD1-OSM feedback cycle develops in the heart of high-fat-diet (HFD)-fed mice following PO, and contributes to the progression of diabetic cardiomyopathy." (PMID 32390875, 2020).
dry eye (1 paper, 2023). "Several genes of the hippo pathway, including YAP1, TEAD1, or SMAD4, were down-regulated in patients with dry eye." (PMID 38254630, 2023).
Duchenne muscular dystrophy (1 paper, 2016). Duchenne muscular dystrophy (DMD) is a neuromuscular disease characterized by rapidly progressive muscle weakness and wasting due to degeneration of skeletal, smooth and cardiac muscle. "Remarkably, in the mdx mouse model for Duchenne muscular dystrophy, skeletal muscle pathology is significantly ameliorated by TEAD1-overexpression, which is likely contributed in part by an increase in utrophin expression." (PMID 27725085, 2016). "To accomplish this, we bred TEAD1-Tg mice to the mdx mouse, a mouse model of Duchenne muscular dystrophy, which is the most severe form of the muscle wasting diseases." (PMID 27725085, 2016).
emphysema (1 paper, 2023). "In contrast, the downregulated TFs (Mafb, Tead1, Irf8, and Runx3) had the lowest regulatory activity in module 4 of the PPE-induced emphysema model." (PMID 37816708, 2023).
ependymoma (1 paper, 2021). A WHO grade II, slow growing tumor of children and young adults, usually located intraventricularly. "Here, we discovered the regulatory roles of TEAD1 in CD44+ TAMs, further highlighting its potential application in ependymoma immunotherapy." (PMID 34824203, 2021).
Ewing sarcoma (1 paper, 2020). A small round cell tumor that lacks morphologic, immunohistochemical, and electron microscopic evidence of neuroectodermal differentiation. "We demonstrate that TEAD1 siRNA shifts Ewing sarcoma cells significantly lower on PHATE_1, toward the pluripotent/neuroectodermal branch." (PMID 32290418, 2020). "We found that inhibition of TEAD1 pushes Ewing sarcoma lower on PHATE_1, indicating that this antagonism is likely bi-directional." (PMID 32290418, 2020).
gastric tumor (1 paper, 2024). "Single-cell RNA-Seq analysis of murine gastric tumors demonstrated varied expression patterns of the Hippo pathway transcriptional complex members, namely, Yap1, Taz, and Tead1, in gastric tumor cells." (PMID 37957015, 2024). "As with the gastric tumor subtypes, expression of TEAD1, but not that of YAP1 or STAT3, varied across the TME subtypes." (PMID 37957015, 2024).
hand osteoarthritis (1 paper, 2021). "Notably, we identified another new THR and hand osteoarthritis-associated signal located in such a transcription factor, the TEAD1 gene, indicating a common molecular pathway underlying both signals." (PMID 34450027, 2021).
HCMV infection (1 paper, 2025). "HCMV infection reduces TEAD1 activity through four distinct mechanisms: closing of TEAD1-bound chromatin, reduction of YAP1 and phosphorylated YAP1 levels, reduction of TEAD1 transcript and protein levels, and alteration of TEAD1 exon 6 usage." (PMID 40928347, 2025). "We selected TEAD1 to represent the TEAD family because it is the only member whose expression levels are significantly altered by HCMV infection." (PMID 40928347, 2025). "Likewise, TEAD1 protein levels decreased (3.7-fold, p < 0.0009) with HCMV infection." (PMID 40928347, 2025). "We confirmed alterations in expression levels at the protein level for the classic TEAD1 targets Thrombospondin 1 (THBS1) and Cellular Communication Network Factor 1 (CCN1), both of which were substantially downregulated upon HCMV infection." (PMID 40928347, 2025).
Hepatic steatosis (1 paper, 2024). Steatosis is a term used to denote lipid accumulation within hepatocytes. "Thus, TEAD1 emerged as a new therapeutic candidate whose inhibition ameliorates hepatic steatosis." (PMID 38459198, 2024).
hypopharyngeal squamous cell carcinoma (1 paper, 2023). "In addition, NSUN2 promotes hypopharyngeal squamous cell carcinoma (HPSCC) by m5C-methylating oncogenic TEAD1 (TEA domain transcription factor 1) mRNA, which upregulates its expression level." (PMID 37325635, 2023).
intestinal tumours (1 paper, 2021). "We next sought to directly test whether TEAD1/4 and TEAD2 are induced upon activation of Wnt signalling in ApcMin mutant intestinal tumours." (PMID 33950519, 2021).
liver disease (1 paper, 2025). "TEAD1, overexpressed in patients with metabolic dysfunction–associated steatotic liver disease, influences cellular lipid content, with its knockdown leading to significant reductions." (PMID 40662169, 2025).
metastatic tumor (1 paper, 2022). "Collectively, our analysis of single cell sequencing data suggested that the TME of primary tumor of NSCLC are enormously immunosuppressive than the metastatic tumor and are populated by high expression levels of EGFR/MAP2K1/MTOR/TEAD1/YAP1 within tumor microenvironment of NSCLC." (PMID 35655775, 2022).